LMNA (lamin A/C)
Diseases named in the same sentence as LMNA in open-access papers (continued):
Sharing a sentence is not in itself a finding about the gene and the disease.
cancer (continued). "LMNA::NTRK1 fusion has also been implicated as the driver pathogenetic event in a wide spectrum of tumors of various lineages and risk of malignancies, including carcinomas, melanocytic Spitz lesions, as well as benign and malignant mesenchymal neoplasms." (PMID 36801905, 2023). "In view of this, lamin A/C behaves similar to an onco-suppressor factor in this type of cancer." (PMID 35883635, 2022). "In our study, LMNA protein expression was significantly downregulated in HY vs. control groups, suggesting that LMNA might lead to cancer progression." (PMID 35805203, 2022). "Likewise, a previous study has shown that reduced expression of lamin A/C, a protein known to promote cell stiffness, also has the effect of sensitizing cancer cells to FSS." (PMID 33526716, 2021). "Other diseases like cancer can also occur when LMNA gene expression is dysregulated." (PMID 30450357, 2018). "The heterogeneous expression of lamin A/C has been described, primarily using western blots and immunohistochemical staining, in cancer cells obtained from colorectal, gut, gastric, lung, breast, prostate, testis, skin hematologic, cervical, endometrial and ovarian tumors." (PMID 28806747, 2017). "In addition, lamin-A/C is involved in cancer development and survival." (PMID 36012358, 2022). "Collectively, our results predict that lamin A/C deficiency does not provide any migratory advantages to cancer cells reaching the lung vasculature but reduces their metastatic potential in the lungs at a post extravasation step, possibly at the level of proliferation inside spheroids." (PMID 34069191, 2021). "As lamin A/C plays many roles in the cell, including regulating gene expression, participating in signaling pathways, and maintaining proper nuclear shape, it is likely lamin A/C also plays a role in the development and/or maintenance and propagation of cancer cells." (PMID 33316938, 2020). "Overall, moderately inhibiting lamin A/C allowed the cells to be deformable enough to easily pass through the pore while still having enough plasticity not to be permanently damaged, showing how both over and underexpression of lamin A can lead to decreased metastatic potential in cancer cells." (PMID 33316938, 2020). "Therefore, as lamin A/C lends mechanical stability to the nucleus, lamin A/C upregulation in some cancers could allow circulating tumor cells from these cancers to withstand fluid shear stress in circulation better, leading to more effective metastasis." (PMID 33316938, 2020). "We determined whether cancer cells also harbor mutant lamin A (progerin) using RT-PCR with primers that can simultaneously detect both the full-length (F) LMNA mRNA (510 bp) and the truncated (T) LMNA isoform/progerin (360 bp)." (PMID 21106101, 2010). "As for the DNA methylation, the cancers and the corresponding genes with hypermethylation were as follows: BRCA: VWF and ITGB3; COAD: QKI, DUSP9, and CNKSR2; KIRC: CNKSR1; PRAD: VWF, LMNA, and ITGB3; UCEC: ITGB3 and APBBAIP." (PMID 38217548, 2024). "Importantly, Pd-TAT in the perinuclear region could trigger the overexpression of lamin A/C proteins to elevate nuclear stiffness and inhibit cancer metastasis, because lamin A/C proteins are highly related to nuclear stiffness and lack of the proteins facilitates cell migration." (PMID 34041494, 2021). "In a similar study of NTRK fusions in cancer patients, those harboring fusions with any of the 3 most frequent partners ETV6, TPM3, and LMNA comprised 22.3% (198/889) of all NTRK‐positive cases, a percentage closer to our observation with MET (13/122 patients, 10.7%)." (PMID 37326363, 2023). "Additionally, while lamin A/C expression levels are often measured together, some studies have found lamin A and lamin C expression is not always affected equally in some cancers, further complicating lamin A/C’s effect on cancer." (PMID 33316938, 2020).
cancer (continued). "Interestingly, both the SMURF2 and LMNA genes are not frequently altered in human malignancies; however, changes in the expression of these genes are common in many cancers." (PMID 29405587, 2018).
tumor (50 papers, 2001 to 2026). "Here we report lamin A/C, a nuclear lamina protein associated with chromatin remodeling, was one of the critical regulators in cellular reprogramming of tumor‐associated myeloid cells." (PMID 31912614, 2020). "Our hypothesis was that the loss of lamin A/ C might result in a thinner nuclear membrane and an easier ability of deformation to pass through narrow gaps; furthermore, the loss of LMNA up‐regulated the expression of the MMPs, making tumour cells more prone to invasion and metastasis." (PMID 32896989, 2020). "Mechanistically, PCDH10 enhanced GSK-3β phosphorylation at Try216, inhibited aberrant β-catenin activation and upregulated the expression of the tumor-suppressive nuclear envelope protein LMNA expression through direct binding." (PMID 41608634, 2026). "Our study is helpful for extending current findings regarding transcriptional activation of ARSs and involvement of tRNA processing in MAS, and suggests the LMNA/c‐Myc axis as a prospective vulnerability for tumour treatment." (PMID 38769668, 2024). "In clinical NB tissues, co‐localisation of LMNA and c‐Myc was also noted at nuclear periphery and intranuclear foci of tumour cells, which was more frequent in specimens with well differentiation." (PMID 38769668, 2024). "During tumor initiation, knockdown of lamin A/C in human neuroblastoma cells increases the population of tumor-initiating cells." (PMID 37864030, 2023). "The tumor center was characterized by a higher abundance of LMNA (two proteoforms), dihydropyriminidase-related protein (DPYSL3), tubulin beta (TUBB), myosin light chain 3 (MYL3), and galectin-1 (LGALS1)." (PMID 35512017, 2022). "Because lamin A/C knockdown nuclei can be more easily deformed and preferentially squeeze through rigid confinements, it has been postulated that tumor cells with low expression levels of these lamins can more readily invade tissues." (PMID 34069191, 2021). "Our study successfully linked the LMNA gene expression and the expression of P16 and CDK1 in HepG2 and 293T cell lines, providing a basis for exploring the relationship between LMNA gene and tumorigenesis in various tumour types." (PMID 32896989, 2020). "After concluding that the LMNA gene knockout resulted in a decrease in the tumorigenic capacity of tumour cells, the relevant molecular mechanism was investigated." (PMID 32896989, 2020). "The role of LMNA gene in tumours, in the development and progression of HCC and its molecular mechanism is still a challenge." (PMID 32896989, 2020). "For example, as lamin A/C plays such an important role in maintaining a cell’s structure, it has been found that lamin A/C can help strengthen circulating tumor cells (CTCs) from stresses they encounter while in circulation." (PMID 33316938, 2020). "On the other hand, LMNA down‐regulates the expression of P16 (the tumour suppressor gene), resulting in the up‐regulation of CDK1." (PMID 32896989, 2020). "The results showed that the LMNA gene was abnormally expressed in many tumours, and the survival rate of the HCC patients with a high expression of the LMNA gene was significantly reduced compared with the rate in patients with a low LMNA expression." (PMID 32896989, 2020). "Subsequent experiments of tumour formation in nude mice also demonstrated that LMMA expression promoted tumour growth while LMNA knockout inhibited tumour growth." (PMID 32896989, 2020). "Then the expressions of CNOT1 and LMNA in the tumor tissues of tumor‐bearing mice were detected by IHC analysis." (PMID 28188704, 2017). "Excitingly, a series of experiments demonstrated that lamin A/C is necessary for a generally known tumour suppressor – pRB stabilization, and decreased expression of lamin A/C results in reduced activity of pRB." (PMID 19144202, 2009).
tumor (continued). "The finding that expression of lamin A/C in patient tumours is closely correlated with CRC related mortality was unexpected and to some extent counter intuitive." (PMID 18714339, 2008). "We then showed that knockout of LMNA could attenuate the tumor growth–promoting effect of NaCr treatment in cells and mice." (PMID 35977926, 2022). "In this work, LMNA protein expression in HepG2, and cells was significantly up‐regulated suggesting that the LMNA gene might be relate to the malignant degree of tumour cells." (PMID 32896989, 2020). "The nuclear import of Nestin suggested that it could directly regulate lamin A/C-dependent nuclear deformation and tumor senescence." (PMID 30190500, 2018). "Overexpression of LMNA could rescue CNOT1 knockdown‐mediated tumor inhibition and Hedgehog signaling pathway inhibition." (PMID 28188704, 2017). "Therefore, it was proved that the loss of LMNA gene expression resulted in the up‐regulation of P16 and down‐regulation of CDK1, suggesting that the loss of the LMNA gene caused the proliferation and cell cycle arrest of the tumour cells." (PMID 32896989, 2020). "Thus, our conclusion was that the knockout of the LMNA gene in different cells has a different effect on cell proliferation and cell cycle, thus potentially explaining the different role of LMNA in different tumours." (PMID 32896989, 2020). "The transcriptome analysis showed that the COAD tumors had more lamin transcripts than normal tissue, supporting the upregulation of LMNA, LMNB1, and LMNB2 expressions in tumor tissues." (PMID 40708945, 2025). "Three of the fusion partners among adults with CRC harboring an NTRK gene fusion tumor have been commonly reported in the literature, including TPM3::NTRK1, TPR::NTRK1, and LMNA::NTRK1." (PMID 38967220, 2024). "Six proteins (LMNA, LCP1, HSPD1, CS, CA1, and ALB) were previously identified as differentially expressed between the tumor center and margin." (PMID 35512017, 2022). "We measured lamin A/C protein amount and we found that it is generally expressed at low levels, except for LAP-35 cell line, which derives from a PNET tumor and shows a more differentiated phenotype." (PMID 35422060, 2022). "Many proteins involved in tumour cell differentiation, such as ribosomal protein 19 (RPS-19), lamin A/C (LMNA) and immunoglobulin heavy constant mu (IGHM), exhibited decreased expression upon cell treatment with activated PSC secretome." (PMID 30923340, 2019). "Consequently, the expression of LMNA is speculated to influence tumor progression." (PMID 21448288, 2011). "Therefore, when tumor cells resist apoptosis signals by upregulating BCL2L11, AKT1, and LMNA genes, they simultaneously exhibit reduced responsiveness to lipid receptor activity." (PMID 39381047, 2024). "Corresponding m/z from collagen type I alpha 2 (COL1A2), cathepsin (CTSG), elongation factor 1-alpha 1 (EEF1A1), EH domain-containing protein 2 (EHD2), epiplakin 1 (EPPK1), prelamin-A/C (LMNA), and prolargin (PRELP) showed higher intensity distribution in HND in comparison to LND tumour areas." (PMID 40603632, 2024). "Taken together, these results demonstrated that SAHA may elicit anti-tumor activity in NPC cells via regulating both phosphorylation and acetylation of WSTF and LMNA at specific residues." (PMID 35591851, 2022). "It is interesting to note that this analysis did not indicate any predicted activation relationships; rather, relationships related to inhibition (for seven proteins: LMNA, NME1, PKM, S100A4, SERPINA1, VIM, and AHCY) were indicated for both increased and decreased proteins in the tumor." (PMID 35512017, 2022). "Although HDL may not directly participate in the tumor cells’ response to the immune system, our study suggests that it can act as an indicator, with the LMNA gene being the culprit behind this phenomenon." (PMID 39381047, 2024).
tumor (continued). "We measured LMNA expression by RT-QPCR using oligos recognizing both lamin A and lamin C. This analysis shows that the levels of LMNA mRNA are significantly reduced in the three tumor cell lines (HeLa, A549, and MCF7), as compared to non-transformed cells (wild type, HGPS and EDMD2)." (PMID 36096808, 2022). "In contrast, low lamin-A,C facilitates tumor cell invasion and tumor growth, and recent analyses of TCGA patient data show that LMNA is lower than adjacent normal tissues in more than half of tumor types, consistent with prior analyses of protein in lung cancer and breast cancer." (PMID 35719698, 2022). "In the present study, we found that the overexpression of the LMNA gene could discriminate GBM patients with a poorer prognosis, specifically in tumours belonging to Classical, Neural and Proneural but not in Mesenchymal GBM subtypes." (PMID 34680461, 2021).
cardiac disease (41 papers, 2013 to 2026). "The most frequently occurring disease categories associated with LMNA mutations were skeletal muscle diseases (n = 262 mutations) and cardiac diseases (n = 260 mutations)." (PMID 36552829, 2022). "DCM caused by LMNA mutations remains one of the most aggressive and lethal heart diseases because of the complexity of LMNA molecule and cellular heterogeneity." (PMID 33407844, 2021). "Mutations in LMNA cause a highly heterogeneous group of diseases predominantly leading to muscular or cardiac disease, lipodystrophy syndromes, peripheral neuropathy, and accelerated aging disorders." (PMID 32793522, 2020). "Mutations in the lamin A/C gene LMNA are reported to cause a variety of heart diseases including SND." (PMID 30538641, 2018). "All five individuals (III-4, proband: IV-2, IV-3, IV-4 and Patient 3) affected with cardiac disease were heterozygous for LMNA nonsense mutation (NM_170707.3: c.736C>T, p.Gln246Stop)." (PMID 29104234, 2017). "While the exact mechanism by which LMNA mutations cause heart disease is under investigation, it is known that the LMNA gene expresses both the Lamin A and C proteins via alternative splicing." (PMID 29149195, 2017). "Other types of LMNA gene mutations are associated with a range of heart disease symptoms including cardiomyopathy, heart failure, and arrhythmia." (PMID 29149195, 2017). "According to a meta-analysis of carriers of LMNA mutations, sudden death was reported in 46% in both patients with cardiac diseases and those with neuromuscular diseases." (PMID 25886484, 2015). "Genetic mutations to the Lamin A/C gene (LMNA) can cause heart disease, but the mechanisms making cardiac tissues uniquely vulnerable to the mutations remain largely unknown." (PMID 34585335, 2021). "In total, 11 LMNA variants were identified in 15 families, and, as expected, phenotype-positive patients showed a complex cardiac phenotype ranging from a predominantly structural heart disease to a highly arrhythmic profile in an apparently normal heart." (PMID 34768595, 2021). "For instance, we could not be certain that all control individuals were excluded, and individuals with psychiatric disease might also have concurrent clinical phenotypes (e.g., heart disease) attributable to LMNA variants." (PMID 28663758, 2017). "However, since there is already strong evidence that LMNA mutations contribute to heart disease in the general population, these variants are of particular interest for functional follow-up." (PMID 28663758, 2017). "For example, Lamin A/C gene (LMNA) gene mutations, which are known to cause a variety of heart diseases, were studied by scRNA-seq of iPSC-CM lines of patients with LMNA (c.357-2A > G) mutations." (PMID 35454155, 2022). "Furthermore, mutations in non-desmosomal genes, including Transmembrane protein 43—luma (TMEM 43), Phospholamban (PLN), Filamin C (FLNC), Desmin (DES), and LMNA (Lamin A/C), have been identified as contributing to the pathogenesis of heart disease." (PMID 40361967, 2025). "For example, there are a variety of LMNA mutations including heterozygous splice site, nonsense, and missense mutation, which cause diverse heart diseases with no other major pathologies." (PMID 29149195, 2017). "As control, we used cardiac muscle tissue from a patient who experienced heart transplantation due to an ischaemic heart disease not related to LMNA mutations." (PMID 27421120, 2016). "Six candidate genes including LMNA, Zinc Finger Homeobox 3 (ZFHX3), Matrix Metallopeptidase 2 (MMP2), Angiopoietin-Like 5 (ANGPTL5), Myosin Heavy Chain 7B (MYH7B) and Potassium voltage-gated channel subfamily H member 6 (KCNH6) have been previously linked to heart disease." (PMID 24349489, 2013). "Although there are currently no reports about PRF1 and TENM4 involved in heart disease, we noticed that they may be related to LMNA mutation-associated DCM in our research; therefore, they may be the potential biomarkers of DCM, which needs further verification." (PMID 33407844, 2021).